RNU6-1244P (RNA, U6 small nuclear 1244, pseudogene)
Gene: Small nuclear RNA gene on chromosome 10 (32,394,558 to 32,394,665, reverse strand). Ensembl gene ENSG00000200484.
Homologues: Orthologues: chimpanzee U6 (98% identical), macaque U6 (91% identical), rabbit U6 (74% identical), dog U6 (70% identical). Paralogues in human: RNU6-21P (82% identical), RNU6-1260P (81% identical), RNU6-144P (81% identical), RNU6-15P (81% identical), RNU6-211P (81% identical), RNU6-268P (81% identical), RNU6-310P (81% identical), RNU6-340P (81% identical), RNU6-80P (81% identical), RNU6-1 (80% identical), RNU6-11P (80% identical), RNU6-1316P (80% identical), and 1285 more.